BMI1 (BMI1 proto-oncogene, polycomb ring finger)
Diseases named in the same sentence as BMI1 in open-access papers (continued):
Sharing a sentence is not in itself a finding about the gene and the disease.
prostate carcinoma (continued). "In addition to a role in tumorigenesis, BMI-1 maintains cancer (stem) cell identity in leukemia, multiple myeloma, breast, lung, and prostate cancer." (PMID 23559850, 2013). "NRP2 is necessary for BMI-1 expression, consistent with our previous finding in prostate cancer." (PMID 23436775, 2013). "Serum-BMI1 protein levels in human prostate cancer patients." (PMID 23308129, 2013). "Additionally, recent studies have shown that Bmi1 promotes cisplatin and docetaxel resistance in osteosarcoma and prostate cancer, respectively." (PMID 23209748, 2012). "To further clarify whether EZH2 and BMI1 participated in HOXB13 transcriptional repression in DU145 prostate cancer cells, we constructed EZH2 siRNA and BMI1 siRNA plasmids and transfected them into DU145 cells, respectively." (PMID 22808286, 2012). "The fact that PTEN binds BMI1 and reduces BMI1 function in cultured prostate cancer cells prompted us to examine whether PTEN co-localizes with BMI1 in primary prostate cancer." (PMID 19903340, 2009). "Additionally, PTEN co-localizes with BMI1 more frequently in primary prostate carcinomas compared to normal prostate glands." (PMID 19903340, 2009). "To examine whether BMI1 also up-regulates hTERT activity in prostate cancer, we ectopically expressed BMI1 in DU145 prostate cancer cells using a retrovirus." (PMID 19903340, 2009). "Additionally, BTF3 acts in prostate cancer by inhibiting the degradation of BMI1." (PMID 39707202, 2024). "In addition, in vitro study revealed that overexpression of basic transcription factor 3 (BTF3) could up-regulate BMI1 expression, which is a crucial mechanism for the acquisition of a stem cells-like phenotype in prostate cancer." (PMID 36969009, 2023). "However, BMI1 exerts also some important oncogenic effects in prostate cancer cells through PRC1-independent mechanisms, involving direct binding to AR and consequent inhibition of MDM2-mediated AR degradation and sustained AR signaling in prostate cancer cells." (PMID 31366128, 2019). "Also, BMI1 promotes cell survival and attenuated chemosensitivity to docetaxelin prostate cancer." (PMID 28830551, 2017). "c-Myc, along with other stem cell genes including SOX2, BMI1 and OCT-4, is highly expressed in prostate cancer stem/progenitor cells." (PMID 34094902, 2021). "It was reported that nuclear PTEN inhibits BMI1’s ability to suppress p16INK4a and p19ARF/p14ARF, as well as its ability to upregulate hTERT in DU145 prostate cancer cells." (PMID 33804165, 2021). "Bmi-1 inhibition protects prostate cells from FGF-10-driven hyperplasia and slows the growth of prostate cancer." (PMID 33584271, 2020). "Particularly, inhibition of BMI1 protects prostate cells from FGF10-induced hyperplasia and reduces the growth of aggressive PTEN-deletion-induced prostate cancer." (PMID 31366128, 2019). "Myc, along with other stem cell genes like SOX2, BMI1 and OCT-4, is highly expressed in prostate cancer cells having the CD44+/CD24– phenotype, which is considered a hallmark of stem/progenitor cells." (PMID 31143708, 2019). "BMI1 binds the androgen receptor (AR) and prevents MDM2-mediated AR protein degradation, resulting in sustained AR signaling in prostate cancer cells." (PMID 29402932, 2018). "In this study, we discovered that BMI1, independently of the PRC1 complex, binds and stabilizes AR proteins to regulate the AR pathway in prostate cancer." (PMID 29402932, 2018). "It has been reported that the newly developed BMI1 inhibitor PTC209 effectively decreased colon, lung, and prostate cancer stem cell-mediated tumor growth." (PMID 29402932, 2018). "In prostate cancer, overexpression miR-203 controls proliferation, migration and invasion by directly targeting ZEB2, Bmi-1, survivin and LASP1." (PMID 29228583, 2017).
prostate carcinoma (continued). "This upregulation occurs concurrently with a downregulation of INK4A and ARF in prostate cancer, NSCLC, and colon cancers, supporting the notion that repression of the INK4A/ARF locus contributes to BMI1-stimulated tumorigenesis." (PMID 26633535, 2015). "BMI1 has been shown to suppress the expression of the INK4A/ARF locus, p16INK4A and p14ARF, which we have also demonstrated recently in prostate cancer cells." (PMID 19903340, 2009). "Our data suggest concurrent targeting of BMI1 and CDK4/CDK6 might provide novel therapeutic opportunity for breast, colon, and prostate cancer." (PMID 31548560, 2019). "miR-128 targets BMI1 mRNA, and therefore it is not surprising that BMI1 protein levels are increased in prostate cancer cells, where miR-128 levels are decreased." (PMID 31366128, 2019). "To further investigate the PRC1-independent BMI1 function in prostate cancer, we demonstrated that the BMI1-truncated mutant, BMI1ΔRING, which does not contain the RING domain and cannot interact with RING1B, still directly interacts with AR NTD." (PMID 29402932, 2018). "For example, the antioxidant enzyme Peroxiredoxin II regulates VEGF signaling in liver CSCs by upregulating BMI1 and Sox2 through a VEGFR-2/STAT3 pathway, while VEGF and VEGF receptor neuropilin-2 signaling involved a BMI1-mediated mechanism in aggressive prostate cancer." (PMID 30002682, 2018). "We analyzed 113 AR-regulated genes derived from cell lines, human prostate cancer, and castration-resistant prostate cancer tissues, and found that their expression levels were significantly dysregulated by BMI1 knockdown, but not by RING1B knockdown." (PMID 29402932, 2018). "This may be attributable to the observed increases in the co-localization between PTEN and BMI1 in PINs and PTEN-positive prostate carcinoma in comparison to normal prostate epithelium." (PMID 19903340, 2009). "The increased co-localization of BMI1 and PTEN observed in PIN lesions and PTEN-positive prostate carcinomas compared to normal prostate epithelium supports this hypothesis." (PMID 19903340, 2009). "As Bmi1 is not exclusively expressed in the prostate epithelium, it is possible that Pten deletion in non-prostate Bmi1-expressing cells, for example, in the microenvironment, might have influenced prostate cancer development in BC-Pten mice." (PMID 27703144, 2016). "This study only explored the effect of BMI-1 O-GlcNAcylation on prostate cancer cell proliferation, apoptosis, and invasion, and thus it is not clear whether BMI-1 O-GlcNAcylation contributes to prostate cancer tumor-initiation cells." (PMID 31272438, 2019). "Also because BMI1 is directly repressed by miR200c, the transcription of which is directly inhibited by ZEB1, we speculated that the ZEB1-miR200c-BMI regulation pathway may play an important role in prostate cancer development and progression." (PMID 28830551, 2017). "However, in prostate cancer cells, PTEN reduces the function of BMI-1 to prevent tumorigenesis, which can be attributed to its interaction with BMI-1 in the nucleus, indicating that a PTEN/BMI-1 double-negative feedback loop may occur and govern EMT/CSC in certain types of cancer." (PMID 25141911, 2014). "BMI1 also possesses functions independent of CDKN2A repression, including the regulation of genes involved in differentiation and cell contact inhibition in Ewing sarcoma and androgen receptor expression in prostate cancer." (PMID 33523558, 2021). "While PTEN marginally co-localizes with BMI1 in normal prostate epithelial cells, PTEN extensively co-localizes with BMI1 in PIN and in PTEN positive (but not negative) prostate carcinoma, which further demonstrates the specificity of the anti-PTEN antibody used." (PMID 19903340, 2009).
glioblastoma (62 papers, 2010 to 2025). The most malignant astrocytic tumor (WHO grade IV). "In glioblastoma, the aberrant cellular proliferation and self-renewal was associated with decreased expression of miR-128, which targets Bmi-1." (PMID 23056008, 2012). "Furthermore, BMI1 can regulate tumor-initiating capacity of CD133+ glioblastoma stem cells via the activation of integrin alpha 2-associated gene networks." (PMID 35455671, 2022). "In glioblastoma cells, Bmi-1 upregulation is associated with the downregulation of miR-128." (PMID 23056008, 2012). "ITGA2 has been identified as a key downstream target of BMI1 in CD133+ glioblastoma stem cells (GBM-SCs), regulating the characteristics of GBM stem cells." (PMID 39239559, 2024). "For example, BMI1 knockdown in glioblastoma multiforme cells impairs the activation of ataxia telangiectasia-mutated kinase and sensitizes the cells to radiation." (PMID 36362068, 2022). "Given that glioblastoma is highly heterogenous with distinct subtypes, combined inhibition of BMI1 and EZH2 provide much stronger anti‐tumour efficacy than targeting each one alone." (PMID 35851726, 2022). "The inhibitors of Bmi1 can effectively prevent the in vitro self‐renewal of glioblastoma stem cells and markedly extend the lifespan of mice with advanced disease." (PMID 33788424, 2021). "For example, BMI1 is overexpressed and promotes cancer cell self-renewal in multiple cancer types, including acute myeloid leukemia, glioblastoma multiforme (GBM), colorectal cancer (CRC), and epithelial ovarian cancer." (PMID 34706761, 2021). "For ‎example, BMI1 conferred radioresistance to CD133-positive glioblastoma multiform via either ‎interaction with p-ATM, γH2AX, or global chromatin remodeling." (PMID 34268251, 2021). "Consistently, a recent study on glioblastomas shows that combined Bmi1 targeting and another molecular targeting drug proved more effective than either agent alone both in culture and in vivo." (PMID 32884573, 2020). "In glioblastoma, BMI-1 plays an important role in cell proliferation and self-renewal of neural stem cells." (PMID 28968963, 2017). "Similar observation with regard to Bmi1 enrichment in CD133-positive cells was reported in glioblastoma multiforme primary cells and tumor samples." (PMID 26770215, 2016). "Using The Cancer Genome Atlas database and a retrospective data set from patients with glioblastoma multiforme, we found that BMI1 expression levels positively correlated with COX4-1 expression and overall survival." (PMID 25726526, 2015). "BMI1 was enriched at the chromatin after irradiation and colocalized with ataxia-telangiectasia mutated (ATM) kinase and the histone gammaH2AX in glioblastoma cells, an important DNA double strand break (DSB) repair pathway." (PMID 24212792, 2011). "This seems to be in contrast with previous evidence, showing that BMI1 protein sustains glioblastoma CSC self-renewal." (PMID 20920292, 2010). "BMI1 is highly expressed in mesenchymal glioblastoma, a highly migratory tumor subtype." (PMID 38918274, 2024). "Understanding PMT regulation more broadly may aid in identifying treatments that preferentially target specific subtypes, as demonstrated for CDK4/6 or EZH2 inhibition for proneural glioblastomas and DGKα or BMI-1 inhibition for mesenchymal glioblastomas." (PMID 38337036, 2024). "Furthermore, in mesenchymal glioblastoma, ZDHHC18 enhances the stability of BMI1 to promote the survival of glioblastoma stem cells (GSCs) in stressful microenvironments." (PMID 37161425, 2023). "So far it remains unclear of the long‐term effects of BMI1 inhibition alone in anti‐glioblastoma treatment." (PMID 35851726, 2022). "Also, research on transgenic mice showed that Bmi-1 plays an essential role in the formation of glioblastoma." (PMID 36793341, 2022). "The proliferation of glioblastoma cells could be blocked by downregulating EZH2 or BMI1 expression, further highlighting the role of both proteins in cancer development." (PMID 33804165, 2021).
glioblastoma (continued). "Moreover, high levels of BMI-1 were found in human glioblastomas, specifically in the tumor-initiating CD133 positive stem cells, and the knockdown of BMI-1 completely prevented brain tumor formation in mice." (PMID 31382410, 2019). "Furthermore, ICG-Gen@CasNPs/PDT/PTT directed ubiquitination and proteasomal degradation of EZH2 and BMI1 indicates the implication of the polycomb in conferring glioblastoma survival." (PMID 36131972, 2019). "BMI-1 is highly enriched in CD133-positive cells of human glioblastoma multiforme." (PMID 29299167, 2017). "A literature review identified DUSP4, HIF-1α, and COL8A2 as being linked to ERK signaling, and analysis of a published dataset of chromatin immunoprecipitation sequencing (ChIP-seq) data for Bmi1 in neural stem cells and glioblastoma cells identified Dusp4 as a direct Bmi1 target gene." (PMID 29212025, 2017). "Of note, RPS6KA2 was also determined to be a downstream target of BMI1 in glioblastoma stem cells." (PMID 28423600, 2017). "Furthermore, knockdown of the oncogene BMI1 reduces expression of glioma stem cell genes and inhibits glioblastoma formation in vivo." (PMID 24172544, 2013). "Bmi-1 was also recently shown to be a target of miR-128a in glioblastoma." (PMID 20574517, 2010). "In addition, GNA could increase glioblastoma multiforme cell sensitivities to temozolomide by specifically inhibiting BMI1." (PMID 40143150, 2025). "This study raises concerns about the Bmi1 inhibitors that are currently under clinical trials (for diseases including glioblastoma multiforme (GBM), colorectal cancer, head neck squamous cell carcinoma) and suggests a closer look for adverse side effects." (PMID 34943965, 2021). "BMI1 was detected being rapidly recruited to DNA lesions caused by local micro-irradiation using UV laser beam, ionizing irradiation (IR), and hydroxyurea (HU) in a set of cell types, including U2OS, mouse embryonic fibroblasts (MEFs), HeLa, and CD133+ glioblastoma multiforme (GBM) cells." (PMID 26633535, 2015). "A recent founding revealed that BMI1 regulates CD133+ brain tumor‐initiating cells in human glioblastoma stem cells, emphasizing the importance of the CD133‐BMI1 circuit in stemness maintenance." (PMID 37062068, 2023). "Their core members such as EZH2 and BMI1 seem to divide their work in the PN and MES subtype of glioblastoma." (PMID 35851726, 2022). "A1016 is an additional BMI1 inhibitor related to PTC‐596 and has shown similar positive results in glioblastoma." (PMID 33523558, 2021). "Each one of these miRs targets several transcriptional regulators, including the oncogenic chromatin repressors EZH2, BMI1 and LSD1, which are functionally interdependent and involved in glioblastoma recurrence after therapeutic chemoradiation." (PMID 30683859, 2019). "Glioblastoma stem cells rely on multiple key stemness-related proteins such as Nestin, CD133, SOX2, Olig2, BMI1, and ZEB138,39." (PMID 30022047, 2018). "Our results also showed that metformin significantly suppressed self-renewal capacity of glioblastoma stem cells (GSCs), and expression of stem cell markers Bmi1, Sox2 and Musashi1, indicating that metformin can inhibit cancer stem-like properties of GBM cells." (PMID 29467947, 2018). "In the present study, we demonstrated that PTUPB also inhibits the expression of stemness maerkers BMI1, SOX2 and the activation of ERK1/2 in glioblastoma cell lines." (PMID 29152086, 2017). "To confirm miR128-1 targeting of BMI1 and E2F3 in glioblastoma cells, we measured BMI1 and E2F3 expression in U251 and U87 cells after miR128-1 transfection." (PMID 27705931, 2016). "Taken together, these data indicate that miR128-1 directly targets BMI1 and E2F3 in glioblastoma cells." (PMID 27705931, 2016). "In glioblastoma multiforme (GBM) cells, Bmi1 was co-purified with DSB response proteins, such as ATM and the histone γH2AX, and non-homologous end joining (NHEJ) repair proteins." (PMID 22606246, 2012).
glioblastoma (continued). "Surprisingly, some PRC1 components (BMI1, CBX2, CBX7) were downreglated in glioblastoma compared to normal brain." (PMID 20920292, 2010). "Targeting oncogenic chromatin repressors such as EZH2 (Enhancer of zeste 2 polycomb repressive complex 2 subunit), BMI-1, and SUZ12, the cooperative strategy of these microRNAs disrupts critical survival mechanisms in glioblastoma cells and unveils promising therapeutic avenues." (PMID 38419943, 2024). "Moreover, HH is involved in regulating tumor spheroid formations, as observed in the case of glioblastoma (GBM) neurospheres, by controlling NANOG.; nestin, BMI1, and gene expression." (PMID 35205721, 2022). "It has been reported that another BMI-1 inhibitor PTC596, which is efficacious in xenograft tumor models of glioblastoma, fibrosarcoma and leukemia, induces CDK1/2 binding to BMI-1 and CDK1/2-mediated phosphorylation of BMI-1 at N-terminal sites, leading to degradation of BMI-1." (PMID 31640758, 2019). "Interestingly, when cells were grown in 2D, the expression levels of OCT4, BMI1, SOX2 for melanoma cells and of SOX2 for glioblastoma were modulated by BCL-XL overexpression." (PMID 29238043, 2017). "Furthermore, we showed that miR128-1 targeted BMI1 and E2F3, and miR128-1 overexpression down-regulated BMI1 and E2F3 in glioblastoma cells both in vitro and in mouse tumor xenografts." (PMID 27705931, 2016). "Treatment of glioblastoma cells with MA led to the inhibition of GSK3 kinase, resulting in the downregulation of SRSF1/5, PTPB1, and hnRNP with decreased levels of anti-apoptotic genes such as BCL2, BCL-xL, Survivin, MCL1, and BMI1 while increased in Anxa7, a tumor suppressor gene." (PMID 39863145, 2025). "BMI1 regulates development and homeostasis of the mammalian central nervous system (CNS) via maintenance of embryonic and adult neural stem cell (NSC) self-renewal, and it is highly expressed in glioblastoma initiating cells (GIC), the key cellular driver of tumour initiation and maintenance in GBM." (PMID 34316702, 2021). "These analyses revealed a negative correlation between BMI1 and EPHA7 expression levels for the human follicular lymphoma and medulloblastoma datasets, but not for the glioblastoma datasets (and data not shown)." (PMID 27533460, 2016).